SNCAIP (synuclein alpha interacting protein)
Description:
Isoform 2 inhibits the ubiquitin ligase activity of SIAH1 and inhibits proteasomal degradation of target proteins. Isoform 2 inhibits autoubiquitination and proteasomal degradation of SIAH1, and thereby increases cellular levels of SIAH. Isoform 2 modulates SNCA monoubiquitination by SIAH1.
Synonyms: Sph1; SYPH1
Tractability: PROTAC: UniProt records ubiquitination sites on it; ubiquitination databases record sites on it.
Gene: Protein-coding gene on chromosome 5 (122,311,354 to 122,464,224, forward strand). Ensembl gene ENSG00000064692.
Subcellular location: Cytoplasm
Subcellular location (Human Protein Atlas): Cytoplasmic bodies; Nucleoplasm
Pathways (Reactome):
Metabolism of proteins: Amyloid fiber formation
Gene Ontology:
Molecular function: identical protein binding; protein binding; ubiquitin protein ligase binding
Biological process: cell death; dopamine metabolic process; regulation of inclusion body assembly; regulation of neurotransmitter secretion
Cellular component: cytoplasm; cytoplasmic ribonucleoprotein granule; cytosol; neuronal cell body; presynaptic membrane; synaptic vesicle
Genetic constraint (gnomAD): Loss-of-function variants: 36 observed, 74.77 expected, observed/expected ratio (o/e) 0.48, 90% interval 0.37 to 0.64. The upper end of that interval is the gene's LOEUF score, 0.64, which puts it in group 2 of 6, group 1 being the genes least tolerant of losing a copy. Missense variants: 907 observed, 1,052 expected, observed/expected ratio (o/e) 0.86, 90% interval 0.82 to 0.91. Synonymous variants: 384 observed, 416.19 expected, observed/expected ratio (o/e) 0.92, 90% interval 0.85 to 1.
Homologues: Orthologues: macaque SNCAIP (98% identical), chimpanzee SNCAIP (98% identical), dog SNCAIP (92% identical), guinea pig SNCAIP (87% identical), mouse Sncaip (87% identical), rat Sncaip (85% identical), rabbit SNCAIP (85% identical), tropical clawed frog sncaip (68% identical), zebrafish sncaip (43% identical).
Diseases named in the same sentence as SNCAIP in open-access papers:
SNCAIP is named in the same sentence as 28 diseases in open-access papers, as found by Europe PMC text mining. Sharing a sentence is not in itself a finding about the gene and the disease. The quoted sentences say what the papers report.
Parkinson disease (20 papers, 2008 to 2025). A progressive degenerative disorder of the central nervous system characterized by loss of dopamine producing neurons in the substantia nigra and the presence of Lewy bodies in the substantia nigra and locus coeruleus. "The most common focal copy number gain was a tandem duplication of SNCAIP, a gene associated with Parkinson’s disease, exquisitely restricted to group IV alpha." (PMID 36899402, 2023). "The other unique marker of metastasis we identified was SNCAIP, a gene encoded synuclein alpha interacting protein, which was mainly related to Parkinson disease." (PMID 33062672, 2020). "We also compared our data to the NCBI public archive of clinically relevant variants (ClinVar) and found a single de novo SNP in one MShef4 subclone, a C > T transition in the penultimate 3’ exon of SNCAIP—an α-synuclein-interacting protein on chromosome 5q, associated with Parkinson’s disease." (PMID 32251294, 2020). "E2 treatment led to a statistically significant antagonism of IGF1R with the subunits ATP5A1, ATP5G1, and ATP5O of the ATP synthases H+ transporting complexes and reduced the synergistic coupling with the Parkinson's disease SNCAIP (synuclein alpha interacting protein)." (PMID 37594177, 2023). "For instance, we detected BRCA1 in Breast Cancer, Amyloid Precursor Protein (APP) in Alzheimer’s Disease, INS in A1C measurement and Type 2 Diabetes, PCSK9 in LDL cholesterol levels and SNCAIP in Parkinson’s Disease, and the circadian rhythm gene CRY2 in Morning vs. Evening chronotype." (PMID 32678846, 2020).
medulloblastoma (9 papers, 2014 to 2025). A malignant, invasive embryonal neoplasm arising from the cerebellum. "The upregulation of PRDM6 expression in Group 4 medulloblastoma is thought to occur via enhancer hijacking caused by tandem duplication of SNCAIP, which is located approximately 600 kb upstream of PRDM64." (PMID 38992221, 2024). "Structural variants affecting SNCAIP disrupt the local chromatin environment, promoting abnormal gene induction, particularly PRDM6 in medulloblastoma." (PMID 39140252, 2025). "We confirmed SNCAIP as exclusively expressed in Group 4 medulloblastoma, and we also identified SLC6A3 as a significantly over-expressed and highly connected pathway member." (PMID 25412507, 2014). "SNCAIP duplication may promote Group 4 medulloblastoma via induction of PRDM6, a poorly characterized member of the PRDF1 and RIZ1 homology domain-containing (PRDM) family of transcription factors." (PMID 38992221, 2024). "In the G4 medulloblastomas, SVs affecting GFI1 and GFI1B and the recurrent tandem duplication of SNCAIP are known to cause overexpression of GFI1, GFI1B and PRDM6, respectively, by putting them under the control of super-enhancer regions (termed enhancer hijacking, EH)." (PMID 37576901, 2023). "Moreover, it is located 600 kb downstream of the SNCAIP locus, a hotspot for tandem duplications that are unique to group 4 medulloblastoma." (PMID 37568705, 2023). "Interestingly, group 3/4 medulloblastomas with amplification of MYC or MYCN or duplicated SNCAIP had significantly higher SNV densities at both ECA and MRCA than the remaining tumours, suggesting that later onset of (pre-)malignancy may predispose to the subsequent acquisition of these drivers." (PMID 40335697, 2025). "Semaphorin (co-expression network, p<1.23×10−5) and dopamine (intersect analysis, p<0.02) signaling pathways were exclusively enriched in Group 4 medulloblastoma and connected via co-expressed genes, DPYSL4, RND2 and SNCAIP that are all part of the same network cluster." (PMID 25412507, 2014).
bladder cancer (1 paper, 2020). "In bladder cancer, SNCAIP was dysregulated and identified as a hub gene for predicting disease progression and prognosis." (PMID 33062672, 2020).
breast invasive ductal carcinoma (1 paper, 2021). "SNCAIP mutation is mostly found in cutaneous melanoma but also occurs in breast invasive ductal carcinoma." (PMID 34445568, 2021).
chronic kidney disease (1 paper, 2021). Impairment of the renal function secondary to chronic kidney damage persisting for three or more months. "Hence, our current findings, together with the previous reports on SNCAIP, propose that duplications of chromosomal band 5q23.2 comprising SNCAIP and single variants within SNCAIP are involved in genitourinary tract anomalies or chronic kidney disease." (PMID 34573432, 2021).
colorectal cancer (1 paper, 2020). A primary or metastatic malignant neoplasm that affects the colon or rectum. "Promoter hypermethylation of SNCAIP could serve as a marker for colorectal cancer identification." (PMID 33062672, 2020).
mood disorder (1 paper, 2015). A cognitive disorder a disturbance in which the person's mood is hypothesized to be the main underlying feature. "rs6867820, another SNP that showed association with mood disorder in our analyses, lies 55 kb from the SNCAIP gene, which encodes Synphilin-1." (PMID 25897833, 2015).
pancreatic cancer (1 paper, 2020). "A previous study revealed that SNCAIP mutations were uniquely found in the diabetic group in pancreatic cancer, mainly involved in immune-related pathways." (PMID 33062672, 2020).
tumor (8 papers, 2020 to 2025). "Due to the deficiency of research, the oncogenic or tumor suppressor role of SNCAIP was not well depicted." (PMID 33062672, 2020). "Last, we examined tumours with enhanced PRDM6 expression (subgroups VII/VIII), in which SNCAIP gene duplication leads to aberrant activation of PRDM6 by means of enhancer hijacking." (PMID 40335697, 2025). "Our prognostic signature include four genes, SERPINE2, SNCAIP, NMU, and S100A9, each playing a critical role in tumor progression, invasion, and metastasis." (PMID 37691944, 2023). "In contrast to tumors, the adjacent non-tumor tissues harbored eight genes with recurrent HBV integration, including FN1, DCC, OAZ2, ANO3, ENOX1, GRIK4, NPAT, and SNCAIP." (PMID 34209079, 2021). "Moreover, NGS analysis indicated upregulation of SNCAIP in tumor-derived ECs, which is almost exclusively expressed in triple-negative breast tumors (protein atlas), suggesting the tumor-related phenotype of the obtained cell lines." (PMID 34445568, 2021).
SNCAIP also shares sentences with these, for which no sentence is quoted: Obesity (5 papers); Insulin resistance (3); Synucleinopathies (3); Alzheimer disease (2); cancer (2); neurodegenerative disease (2); amyotrophic lateral sclerosis (1); breast carcinoma (1); cutaneous melanoma (1); dementia (1); diabetic kidney disease (1); glioma (1); hepatocellular carcinoma (1); Hydrocephalus (1); neuroblastoma (1); Parkinsonism (1); tauopathy (1); Tremor (1); Type 2 Diabetes (1).